SIRT3 (sirtuin 3)
Diseases named in the same sentence as SIRT3 in open-access papers (continued):
Sharing a sentence is not in itself a finding about the gene and the disease.
Obesity (continued). "Compared with WT mice, Sirt3-KO mice fed an HFD show accelerated obesity, insulin resistance, hyperlipidemia, and hepatic steatosis." (PMID 30574122, 2018). "Our results indicated that myricetin exerted anti-obesity effects through the upregulation of Sirt3 expression and mitochondrial metabolism in adipose tissue." (PMID 30545041, 2018). "The central finding of this study is the upregulation of Sirt3 expression as a molecular mechanism of the anti-obesity effects of myricetin." (PMID 30545041, 2018). "We provide evidence that chronic inhibition of PIKfyve by STA attenuates obesity‐related cardiometabolic phenotype by reducing mitochondrial oxidative stress and apoptosis through the deacetylase SIRT3." (PMID 28396567, 2017). "We provide evidence that PIKfyve inhibition reverses obesity‐induced cardiac mitochondrial damage and apoptosis by activating SIRT3." (PMID 28396567, 2017). "We further identified SIRT3 as a critical player in obesity-induced vascular insulin resistance and resultant endothelial dysfunction." (PMID 27000941, 2016). "The aim of this study was to investigate the role of SIRT3 in endothelial insulin resistance and vascular dysfunction in obesity." (PMID 27000941, 2016). "However, the role of SIRT3 in obesity associated endothelial dysfunction remains unknown." (PMID 27000941, 2016). "Wild-type (WT) and SIRT3 knockout (SIRT3 KO) mice were fed with HFD for 16 weeks to develop a diet-induce obesity (DIO) model." (PMID 25782072, 2015). "Our study thus identifies SIRT3 as a potential therapeutic target for preventing obesity-induced cardiac dysfunction." (PMID 25782072, 2015). "Our study demonstrates the importance of SIRT3 in preserving heart function and capillary density in the setting of obesity." (PMID 25782072, 2015). "Our recent study adds to the understanding of SIRT3 metabolic function in the context of metabolic stress induced by high fat diet and obesity." (PMID 21386135, 2011). "Impaired SIRT3 function results in the accumulation of long-chain acylcarnitine, which is consistent with the elevated plasma long-chain acylcarnitine levels in patients with obesity." (PMID 41304967, 2025). "Activating SIRT3 in adipocytes could be a potential strategy to alleviate obesity-related metabolic diseases." (PMID 40368890, 2025). "Endothelial SIRT3 loss contributed to diet-induced BAT whitening and obesity progression and thus, could be a therapeutic target in treating obesity and associated metabolic diseases." (PMID 40520025, 2025). "Here in our study, the loss of endothelial Sirt3 exacerbated HFD-induced BAT whitening and obesity progression through impaired angiogenesis and dysregulated paracrine profiles, which, therefore, suggesting the participation of cardiovascular system in modulating overall metabolism." (PMID 40520025, 2025). "In addition, an in vivo study investigating the effects of aerobic exercise on obesity showed that elevated SIRT3 expression contributes to weight improvement by activating pathways that regulate mitochondrial homeostasis." (PMID 41304967, 2025). "Furthermore, in mouse obesity models, reduced SIRT3 expression correlates with elevated ROS levels, while SIRT3 overexpression mitigates ROS production, reducing spindle defects and chromosome misalignment." (PMID 38731898, 2024). "Additionally, HFD-fed Sirt3−/− mice display obesity-related cardiac dysfunction, cardiac remodeling, and elevated cardiac inflammation via modulation of the ROS-NF-κB-MCP-1 pathway." (PMID 36675125, 2023). "A future animal model study would be interesting in revealing whether Sirt3 activator works in concert with other physiological processes for improving obesity-induced insulin resistance and other metabolic disease states." (PMID 35409099, 2022). "Aging and obesity decrease the SIRT1-regulated deacetylation of SIRT3." (PMID 34829803, 2021).
Obesity (continued). "Oleic acid, which is the main product of Scd-1 reaction and associates Scd-1 with the development of obesity and the metabolic syndrome, was significantly decreased in SFD-fed ovx KO mice (* p < 0.05), making all three main MUFAs reduced upon Sirt3 and ovary hormone deficiency." (PMID 33924115, 2021). "SIRT3 expression and enzymatic activity are reduced in aging and obesity." (PMID 34829803, 2021). "Decreased SIRT3 expression during NAFLD could be due to palmitic acid—levels increase during obesity—that downregulates SIRT3, thus resulting in oxidative stress and apoptosis in the liver." (PMID 33806509, 2021). "In our study, SIRT3TG mice, which overexpress SIRT3 in cardiac and skeletal muscle, displayed obesity, glucose intolerance, impaired cardiac function, and adverse cardiac remodeling to the same extent as WT mice when both were subjected to 4 months of HFHS feeding." (PMID 34405591, 2021). "Therapeutic strategies targeting SIRT3 might, therefore, be useful to prevent the development of obesity and/or T2D in humans." (PMID 34405591, 2021). "Whether or not CypD expression in the brain is elevated with a corresponding reduction in SIRT3 during obesity is unknown." (PMID 33092099, 2020). "Macroautophagy and CMA play an important role in the protective effect of SIRT3 against lipid accumulation in adipocytes, and SIRT3 might be a therapeutic target to optimize obesity treatment." (PMID 31936019, 2020). "We found that CA promotes activation of BAT function and differentiation by upregulation of genes related to BAT thermogenesis, mitochondrial biogenesis and mitochondrial activation such as Pgc1a, Ucp1, Prdm16, Sirt3, Cidea and CytC, thereby suppress obesity by promoting EE." (PMID 31443565, 2019). "Also, sirtuin-3 (SIRT3) has been proposed as a major control point for obesity-related metabolic diseases and it can regulate the activity of some of these genes." (PMID 26619907, 2015). "This study investigated the functional role of SIRT3 in obesity-induced cardiac dysfunction." (PMID 25782072, 2015). "Sirt3−/− mice developed accelerated obesity, insulin resistance, and hyperlipidemia." (PMID 24370889, 2014). "Decreased expression of SIRT3 and other key mitochondrial proteins involved in fatty acid oxidation and OXPHOS suggest mitochondrial dysfunction may precede more detrimental obesity associated co-morbidities such as insulin resistance and NAFLD." (PMID 21901160, 2011). "Conversely, a decline in mNAD+ levels during aging or in response to obesity, leading to lower SIRT3 activity, could explain the decline in heart function during aging and why obesity accelerates this decline." (PMID 21212461, 2010). "Enhancing SIRT3 level and/or mimicking its activity in AT could offer hope for more effective and targeted interventions to ameliorate systematic inflammation and combat obesity-related metabolic diseases." (PMID 40368890, 2025). "Moreover, pharmacological and genetic inhibition of SIRT3 in obesity models drives proinflammatory macrophage polarization by inducing mitochondrial dysfunction and excessive ROS, providing direct evidence that SIRT3 loss in macrophages can amplify systemic inflammatory tone." (PMID 41465170, 2025). "The ability to upregulate SIRT3 to maintain mitochondrial integrity and antioxidative defense mechanisms offers potential therapeutic interventions for tackling age-related declines in oocyte quality and mitigating the impacts of metabolic disorders like obesity and PCOS on fertility." (PMID 39329773, 2024). "Therefore, we speculate that Sirt3 may be important for iBAT thermogenesis in response to cold, while it is dispensable for iBAT upon normal condition or diet‐induced obesity." (PMID 39348266, 2024). "Overexpression of SIRT3 could reduce ROS accumulation in oocytes of the mouse with obesity." (PMID 38653987, 2024).
Obesity (continued). "Furthermore, AR-C17 has been shown to have protective effects on adipocyte mitochondrial dysfunction by promoting Sirt3-mediated autophagy, and AR-C17 could be considered a potential dietary functional ingredient for preventing obesity." (PMID 37960251, 2023). "SIRT3 might be a promising target for the treatment of obesity and related metabolic dysfunction." (PMID 35571098, 2022). "Thus, SIRT3 has been suggested as a potential therapeutic target for preventing the development of diet‐induced obesity and mitigating its pathological effects, including obesity‐related cardiac dysfunction." (PMID 34405591, 2021). "Thus, KLF15/PPARα may interact with Sirt3 to regulate Sirt3 activity or expression in response to obesity and thus regulate ACADVL acetylation." (PMID 30061171, 2018). "Thus, diet-induced obesity SIRT3 KO (SIRT3 KO-DIO) mice may be useful as a novel model to study HFD-induced heart failure in ageing." (PMID 25782072, 2015). "In summary, ALM attenuates inflammatory crosstalk between M1 macrophages and adipocytes by enhancing SIRT3-mediated mitophagy and suppressing NLRP3 inflammasome activation, thereby alleviating adipose tissue inflammation and pathological remodeling in obesity." (PMID 41372934, 2025). "Our previous study revealed that Sirt3 knockout exacerbates HFD-induced BAT whitening and obesity progression." (PMID 40520025, 2025). "Overall, these findings suggest that high expression of SIRT1 and SIRT3 and low expression of SIRT2 and SIRT6 produced a metabolic state that inhibited the development of obesity, thereby reducing the occurrence of obesity." (PMID 36581622, 2022). "SIRT3 activity is modulated by the NAD+/NADH ratio, and its expression is decreased in obesity and NAFLD." (PMID 34199098, 2021). "HFD-induced obesity and ageing obliterate SIRT1-mediated deacetylation of SIRT3, which reduces SIRT3 activity and stability in the mouse model." (PMID 33379163, 2020). "In vitro studies have found that SIRT3-deficient brown adipocytes had reduced UCP-1 expression and mitochondrial biogenesis, while a HS diet-induced decrease in SIRT3 impaired mitochondrial biogenesis in BAT, which was correlated with obesity." (PMID 31409767, 2019). "Our study further confirms that HFD-induced obesity and HFD-induced hippocampal neuronal damage are mainly due to decreased SIRT3-MnSOD antioxidative system." (PMID 29765980, 2018). "In a human study, SIRT3 gene expression was decreased in VAT from morbid subjects and WAT from children with obesity." (PMID 30574122, 2018). "Thus, SIRT3 may be a potential therapeutic target for obesity-induced heart failure." (PMID 25782072, 2015). "Therefore, mice with global or BAT regional endothelium-specific Sirt3 knockout were constructed to investigate the effects of endothelial SIRT3 on BAT activity and obesity progression." (PMID 40520025, 2025). "Most studies suggest that SIRT1, SIRT3, and SIRT6 play protective roles in obesity." (PMID 41304967, 2025). "Inducing fatty acid oxidation to reduce lipid storage is another strategy used to combat obesity; thus, food crops or bioactive molecules that modulate fatty acid oxidation regulators such as PPAR‐γ, carnitine palmitoyl transferase (CPT1), and sirtuin 3 (SIRT3) aid in the fight against obesity." (PMID 38455221, 2023). "The methods targeting the SIRT3/SMCT1 pathway may be a promising way to treat kidney diseases related to hyperinsulinemia as in cases of type 2 diabetes and obesity." (PMID 36237185, 2022). "Published reports revealed that obesity and chronic HFD decreased the SIRT3 expression." (PMID 32365537, 2020). "In summary, we found SIRT3 is a positive regulator of macroautophagy and CMA in adipocytes, which might be a promising therapeutic target for treatment of obesity and its related metabolic dysfunction." (PMID 31936019, 2020).
Obesity (continued). "A previous study demonstrated that TGR5 activation inhibited oxidative stress and induced mitochondrial biogenesis by promoting SIRT1, SIRT3, and Nrf-1 expression, indicating a protective role for TGR5 inhibiting obesity-related and diabetes-related kidney disease." (PMID 33298860, 2020). "Mice lacking Sirt3 fed a high fat diet (HFD) showed accelerated obesity, glucose intolerance, insulin resistance, hyperlipidemia, and steatohepatitis." (PMID 33191653, 2020). "Although the role of SIRT3 in WAT lipid metabolism is intricate and unclear, these studies suggest that SIRT3 may play a protective role in obesity." (PMID 30574122, 2018). "Genetic inference or genetic knockout of SIRT3 accelerates diet-induced obesity, type 2 diabetes, and nonalcoholic fatty liver disease." (PMID 28003866, 2016). "However, caloric excess such as in obesity and chronic HFD reduces liver SIRT3 activity, impairs mitochondrial function and induces hyperacetylation of various mitochondrial proteins." (PMID 24837835, 2014). "In contrast, obesity and HFD reduce SIRT1 and SIRT3 activity in vivo." (PMID 24073959, 2013). "Moreover, Sirt3 gene expression was relatively downregulated after Ramadan IF in patients with obesity compared to non-obese controls." (PMID 35334932, 2022). "This is consistent with reports that overexpression of SIRT3 in C57B6 mice liver in vivo did not protect against lipid accumulation induced by HFD, whereas SIRT3 deficient mice fed an HFD show accelerated obesity, insulin resistance, hyperlipidemia, and steatohepatitis compared with WT mice." (PMID 29581157, 2018). "Interestingly, mice lacking SIRT3 under HFD show accelerated characteristics of the metabolic syndrome such as obesity, insulin resistance, hyperlipidemia and steatohepatitis compared to WT." (PMID 24837835, 2014). "The anti-obesity effect of the absence of iNOS is probably due to changes in pathways promoting the differentiation of brown fat cells, and changes in genes involved in brown fat function, such as Sirt1, Sirt-3 and Pgc-1α." (PMID 20532036, 2010). "However, when exposed to extreme stress such as feeding with high-fat diet (HFD) for 12 months (not 1 week or 3 months), Sirt3−/− mice displayed multiple metabolic syndromes including obesity, insulin resistance, hepatic steatosis, nonalcoholic steatohepatitis, or hyperlipidemias." (PMID 34966740, 2021). "SIRT3TG and WT mice developed obesity, glucose intolerance, cardiac dysfunction, and pathological cardiac remodeling after 4 months of HFHS feeding, indicating muscle‐specific SIRT3 overexpression does not attenuate the pathological effects of HFHS‐feeding." (PMID 34405591, 2021).
heart failure (76 papers, 2011 to 2025). Inability of the heart to pump blood at an adequate rate to meet tissue metabolic requirements. "SIRT3 is an essential mitochondrial enzyme implicated in energy balance, cardiac remodeling, and heart failure." (PMID 41567643, 2025). "Age-related declines in SIRT3 activity are associated with increased susceptibility to cardiovascular diseases, such as heart failure and arrhythmias." (PMID 40799515, 2025). "Like SIRT1, the declined activity of SIRT3 associated with aging is associated with endothelial dysfunction, hypertension, and heart failure." (PMID 36093141, 2022). "Loss of SIRT3 impairs the contractile function of the heart 117, and in a later study SIRT3 was found to be down-regulated in heart failure." (PMID 32724473, 2020). "In the heart, mitochondrial protein lysine hyper-acetylation was found to be associated with induction of heart failure, and overexpression of SIRT3 protected hearts against hypertrophic stimuli." (PMID 28423723, 2017). "Others have shown that SIRT3 KO mice go into heart failure more rapidly with TAC and are more susceptible to ischemia–reperfusion injury." (PMID 26664907, 2015). "The study by Hafner showed that Sirt3, implicated in lifespan extension in humans, also inhibits aging and makes the heart resistant to oxidative stress and heart failure." (PMID 21248376, 2011). "Taken together, our study demonstrated a potential mechanism for how mitochondrial SIRT3 deficiency in endothelium may promote heart failure and cognitive impairment in aging." (PMID 39425510, 2024). "The loss of endothelial SIRT3-induced reprogramming of glycolytic metabolism may contribute to the development of coronary microvascular rarefaction and heart failure." (PMID 37237500, 2023). "Sirtuin 3 (SIRT3), a key deacetylase in mitochondria, has been demonstrated to be downregulated in the failing heart, and SIRT3 knockout mice are susceptible to develop transverse aortic constriction-induced heart failure." (PMID 36093152, 2022). "SIRT3 activity declines as a result of aging-induced changes in cellular metabolism, leading to increased susceptibility to endothelial dysfunction, hypertension, heart failure and neurodegenerative diseases." (PMID 34829803, 2021). "In addition, in post-infarction heart failure in diabetic rats, reduced SIRT3 expression was associated with increased mPTP opening and acetylation of its activator, cyclophilin D." (PMID 26664907, 2015). "SIRT3 can relieve myocardial damage post-MI by inhibiting mitochondrial fission, whereas overexpression of SIRT3 can delay the progression of heart failure (HF) by improving mitochondrial biological function." (PMID 40893347, 2025). "Research has shown that Daidzein can effectively inhibit DOX‐induced heart failure in mice by suppressing fibrosis, cell apoptosis and oxidative stress, and regulating energy metabolism through the SIRT3/FoxO3 pathway." (PMID 40785055, 2025). "The SIRT3 activator Honokiol improved exercise capacity in a myocardial infarction model mice with heart failure by improving mitochondrial function in their skeletal muscle through the reduction of SOD2 acetylation." (PMID 40511632, 2025). "For example, ablation of endothelial Sirtuin 3 changes glycolysis by disrupting glucose transport from VECs to cardiomyocytes, leading to pressure overload and heart failure." (PMID 40393151, 2025). "SFYX is known to protect against heart failure by activating SIRT3/FOXO1 signaling-mediated mitophagy and apoptosis through deacetylation." (PMID 41567643, 2025). "We also validated the pharmacological mechanism of 2-APQC in the ISO induced SIRT3 knockout H9c2 heart failure cell model." (PMID 38744811, 2024). "Accumulating evidence has recently revealed that SIRT3 plays its critical roles in cardiac fibrosis, myocardial fibrosis and even heart failure (HF), through its deacetylation modifications." (PMID 38744811, 2024).